CD68 (CD68 molecule)
Diseases named in the same sentence as CD68 in open-access papers (continued):
Sharing a sentence is not in itself a finding about the gene and the disease.
tumor (continued). "A quantitative exploration displayed that the number of CD68+ regions in the tumor stroma was greatly higher than that in the normal stroma." (PMID 35090495, 2022). "We found that higher levels of tumour-infiltrating T cell subsets, including CD8+PD-1+LAG-3+TIM-3+, CD4+FoxP3+CTLA-4+ T and CD68+STING+ cells, were associated with inferior overall survival (OS) in 80 patients." (PMID 35982052, 2022). "Since the presence of hyaluronan was regarded as a major reason for the immune evasion of PDAC, abrogation of GFPT1 by DON increased the anti-tumor CD68+ macrophage and cytotoxic T cells, eventually sensitized anti-PD-1 immunotherapy effects." (PMID 36158580, 2022). "On the other hand, the myeloid cell population (CD33), microglia, and macrophages (CD68) were uniformly distributed throughout the tumor microenvironment." (PMID 35203636, 2022). "Multiplex immunohistochemistry assay was performed in seven patients (P01-P06 and P09) to simultaneously measure the expression of the multiple surface markers associated with the tumor microenvironment, such as PD-1, PD-L1, CD3, CD8, CD68, CD56 and CD163." (PMID 35172862, 2022). "Next, we investigated how the 3 key populations of DB-CRCs (CD8+GzB+, CD8+Ki67+, and CD68+CD74+ cells) were distributed across regions of the same tumor." (PMID 34197832, 2021). "In our study, CD8+ T cell/CD68+ M densities were evaluated according to the focal location of cancer tissues, including the tumor center and invasion front." (PMID 33613757, 2021). "Markers for T cell subsets (CD4, CD8, FoxP3), macrophages (CD68), dendritic cells (CD11c), tumor cells (CD4), vasculature (CD31), and epithelium (cytokeratin) were clearly visualized in the CODEX fluorescent images." (PMID 34795254, 2021). "Co-staining of the macrophage marker CD68 with IgE or its receptor FcεRIα revealed increased IgE+CD68+ and FcεRIα+CD68+ cells in the tumor of Prdm1fl/flFoxp3YFP-Cre mice compared to WT mice." (PMID 34798898, 2021). "We performed co-immunostaining of TNFα and CD68 on 13 GBM samples from patients to detect TNFα expression in GAMs per mm2 of tumor section." (PMID 33853689, 2021). "The levels of the second M2 population (CD68+CD163+) were similar in both groups (p = 0.1869 for tumor parenchyma and p = 0.7626 for stroma)." (PMID 33807310, 2021). "As the tumor microenvironment is an important player in tumor progression, we investigated immunohistological expression of TAM (tumor-associated macrophages) using CD163 and CD68 markers in tumors." (PMID 33747916, 2021). "Treatment with CDA was associated with the reduction in expression of HCL tumour markers (CD20, CD11c) and increased expression of myeloid markers (CD14, CD68, CD66b, ARG1)." (PMID 34561502, 2021). "A recent meta-analysis demonstrated that higher CD68(+) TAMs in tumor nests predicted favorable disease-free survival, and higher M2 (CD163(+)) macrophages were associated with poor survival outcomes in NPC." (PMID 34407796, 2021). "Some studies have shown that CD68+ TAMs are mostly distributed in CRC tumor stroma, mainly along the front edge of the invasion, and CD68+ TAMs infiltrated into this site can improve the prognosis of CRC patients." (PMID 34445193, 2021). "Findings reveal, a positive correlation between the CD4+/CD163+ and CD8+/CD68+ T cell ratio which can be attributed to cross talking between macrophage surveillance and T cell signaling in tumor microenvironment." (PMID 34326381, 2021). "Overall, macrophages were the most commonly detected cell type with 69 of 141 tumor ROIs positive for CD68 by DSP and 48 of 141 for CD163." (PMID 33658518, 2021). "In a retrospective study of 123 patients with advanced CRC who were treated with bevacizumab combined with chemotherapy, the RFS and OS rates of CRC patients with low tumor interstitial CD68+ TAMs were significantly higher." (PMID 34445193, 2021).
tumor (continued). "IHC analysis showed a positive association between IRF3 and IRF7 expression and tumor-infiltrating immune cells, including CD4+ T cell and CD68+ macrophages." (PMID 34488791, 2021). "CD68 is exploited as a valuable cytochemical marker to immunostain monocyte/macrophages in the histochemical analysis of tumor tissues." (PMID 34489962, 2021). "An increased CD163+/CD68+ ratio in the tumor invasive front (TF) was positively correlated with shorter RFS and OS rates in CRC." (PMID 34445193, 2021). "We found that VISTA was detectable in tumor-infiltrating CD68+ macrophages, CD3+ T cells, CD19+ B cells, CD4+ T-helper cells, and CD8+ cytotoxic T cells." (PMID 33237432, 2021). "When CD14+, CD68+ and CD163+ myeloid densities in the intratumoral tumor (IT Tumor) increased, the risk of death was found to decrease slightly but in a statistically significant manner." (PMID 34194435, 2021). "The number of CD68+ macrophages was negatively correlated with tumor size and metastasis but positively correlated with tumor recurrence risk and prognosis." (PMID 34956906, 2021). "The expression of NK-3R was observed not only in the tumor cells, but also in the almost osteoclasts, which were correlated with the expression of CD68-positive cells at the tumor bone invasion front." (PMID 34200131, 2021). "The authors also observed accumulated CD68+ microglia cells and macrophages within the tumor bed around viral plaques in G207 injected tumors." (PMID 34206677, 2021). "The relative frequency of CD20, CD3, CD8, and CD68-positive cells within each tumor reflected that uADCs and uLMS exhibited cellular heterogeneity regarding immune distribution, whereas the total amount of infiltrate remained the same in 5 × 4-mm ITF." (PMID 34150764, 2021). "To validate this distribution of macrophages in tumor stroma, we analyzed the expression of macrophage marker CD68 in patient derived tissues." (PMID 34326381, 2021). "Generally, the degree of inflammation measured by the expression of CD68 showed a positive significant correlation with tumor size and tumor growth index." (PMID 34243786, 2021). "It is interesting to note the CD68 expression was independently associated with poor relapse-free survival and CD163 expression was an independent prognostic factor along with tumor thickness." (PMID 34449584, 2021). "Other studies show that the IDH1R132H mutation detection rate increases with largening tumor volumes in glioma patients, while tumor vessel sizes and perivascular CD68 + macrophage density both affect the concentrations of ctDNA in plasma." (PMID 34603383, 2021). "Compared to EBV-negative NPC tumours, the immune-suppressive T regulatory cells (Tregs), CD68+ myeloid cells, and exhausted CD8+ T cell subtypes are found enriched in EBV-positive NPC tumours." (PMID 34956172, 2021). "Regarding to TAMs, it has been revealed that CD68+/CD163 + M2 TAMs progressively accumulated from the tumor nest and distant locations in the TME towards the invasive front of the tumor mass in cutaneous melanoma." (PMID 34183054, 2021). "Two literatures reported the correlation between the total density of CD68+ macrophage cell number in tumor stroma and age of patients." (PMID 33928349, 2021). "PDL1 expression was significantly correlated with high CD68+ M density in the tumor center and invasion front of MSS GC (P = 0.001 and 0.014, respectively)." (PMID 33613757, 2021). "IHC shows that CD68 is expressed either in the tumor or the stroma compartment, and exhibits amoeboid or ramified morphology, whereas CD163+ cells display ramified morphology in the same localizations." (PMID 34200100, 2021). "Immunohistochemical analysis showed that HPV-negative OPSCC contained significantly more neutrophils than HPV-positive tumours, whilst levels of CD68+ macrophages and CD3+ lymphocytes were similar." (PMID 35047989, 2021). "(A) Representative images of IL‐33+ cell, CD206+ cell and CD68+ cell in non‐tumour and tumour tissue (scale bar = 50 μm)." (PMID 33305406, 2021).
tumor (continued). "The expression of CD68 in both TAMs and tumor cells is related to poor clinical outcomes in various types of cancers." (PMID 34079767, 2021). "Our MPH analysis (of the hypoxic and better oxygenated tumor) shows CD68+ cells infiltrate hypoxic tumor regions to a greater extent than the CD8+ cells, supporting previous observations." (PMID 34625491, 2021). "The density of blood vessels and CD68+ macrophages also increased around the low‐grade satellite tumour if a high‐grade index tumour was present." (PMID 33330991, 2021). "CD68 appeared to be the most applicable immune marker to stratify the outcome of chemotherapy for patients categorized by the nodal stage and tumor stage." (PMID 33467469, 2021). "In this report, tumor tissue showed an increased level of macrophage marker CD68 and PAR1 marker F2R." (PMID 34066284, 2021). "CD68 is a pan-macrophage marker, encompassing both the functional M1 (pro-inflammatory and anti-tumour) and M2 (anti-inflammatory and pro-tumour) profiles." (PMID 33769181, 2021). "We observed a significantly higher percentage of CD68+ macrophages (21–27%) in all examined tumor areas when compared to CD45+ leucocytes (ca. 3–7%); CD163+ cell infiltration was between 5 and 15%." (PMID 34654395, 2021). "The 32 samples were also subjected to analysis of CD20, CD4, CD8, CD68, Foxp3 and P16 by multiplex immunofluorescence (mIF) staining, and the immune markers were evaluated in the tumor body (TB), tumor margin (TM) and normal stroma (NS) regions separately." (PMID 35145511, 2021). "Based on this method, we observed that most T cell subsets, CD20 + B cells and CD68+ macrophages were mainly distributed in the central region of the tumor, and CD66b+ granulocytes were predominately enriched in IM." (PMID 34631551, 2021). "Our observation can support this, because we have seen significantly increasing infiltration with CD8+, CD45+ and CD68+ cells in tumours and their vicinity after cryotherapy." (PMID 34281259, 2021). "In NSCLC, TREM-1 expression in tumors was restricted to tumor-infiltrating CD68+ myeloid cells, yet soluble TREM-1 in serum was also reported to have prognostic significance." (PMID 34956864, 2021). "The densities of CD68+ tumor-associated macrophages (TAMs) and CD15+ tumor-associated neutrophils (TANs) were significantly higher in patients with elevated serum CRP levels than in those with low CRP levels (both p < 0.0001)." (PMID 35070979, 2021). "In IBC cases presenting as tumor cell clusters in dermal lymphatic vessels, we observed a dense accumulation of CD68+ macrophages in the dermis." (PMID 34824220, 2021). "We then examined blood vessel (Factor VIII) and macrophage (CD68) densities in non‐malignant prostate tissue surrounding the tumours." (PMID 33330991, 2021). "By using CD68, a pan-macrophage marker, and CD163, an M2-like polarization macrophage marker, immunohistochemistry (IHC) was performed to identify tumor-associated macrophages (TAMs) and CLSs." (PMID 34677277, 2021). "The analysis of CD68+/iNOS-negative TAMs in CRC patients showed that the presence of intensive infiltrations of M2 macrophages, CD163+ and CD68+ TAMs, in the tumor stroma was a bad prognostic, as it correlated with shorter DFS and OS." (PMID 33557173, 2021). "Paired paraffin-embedded tumor samples were used to quantify immune cell populations, such as CD11b+ myeloid cells, CD68+ macrophages (Mφs), CD15+ neutrophils, CD8+ T cells, and CD206+, CD204+, CD163+ and CD169+ Mφs, by immunohistochemistry." (PMID 35070979, 2021). "In this study, viral plaques and CD68+ cells within the tumor tissue were confirmed by immunostaining." (PMID 34206677, 2021). "As a marker related to TAMs, the infiltration of CD68+ cells is supposed to be positively related to tumor severity." (PMID 34858800, 2021). "The expression of four CAF-specific markers correlated positively with that of CD68, CD163, MRC1, IL10, and TGFB1, which are markers that characterize tumor-associated macrophages (TAMs)." (PMID 33799788, 2021).
tumor (continued). "For example, Forssell and colleagues found a high density of CD68 + macrophages along the tumor front to be a good prognostic marker for colon cancer." (PMID 34566638, 2021). "When comparing PD-L1+ cells, average PD-L1 expression intensity was higher on macrophages (CD68+) than on tumor cells (pan-CK+) in both the tumor bed and stromal regions for all patients evaluated." (PMID 34921143, 2021). "A visible number of tumor-associated myeloid cells including CD68+ and CD163+ macrophages and CD33+ myeloid cells were also detected in most tumor tissues." (PMID 34257571, 2021). "In conclusion, CD68+ TAM and CD163+ M2 TAM infiltration in CC were associated with tumor progression." (PMID 33928349, 2021). "CXCR5 has two transcripts, both localized on the cell membrane, and is expressed by follicular helper T cells (Tfh), circulating CD4+ T cells, B cells, CD68+ macrophages, and tumor cells." (PMID 34947813, 2021). "Immunohistochemistry analysis performed in the resected injected tumors revealed extensive tumor necrosis, cellular debris, and tumor infiltration with immunosuppressive macrophages (with increased CD163/CD68 ratio) on the edges of tumor plane." (PMID 34662233, 2021). "The tumor samples were stained for CD68 (total macrophage marker), CD163, CD206, CD204, CHID1 (M2 markers), inducible nitric oxide synthase (iNOS), IDO1 (M1 marker), FoxP3 (Treg marker), CD3 (mature T-cells marker), CD8, and PD-L1." (PMID 33466316, 2021). "Quantification of CD66b and CD68 in the tumor tissues demonstrated that the densities of the CD66b+ TANs were correlated with those of the CD68+ TAMs." (PMID 33692217, 2021). "We also assessed the co-expression of PD-L1 and markers that define specific immune cell subpopulations: CD4 and CD8 for lymphocytes, FoxP3 for regulatory cells, and CD68 for macrophages, as well as PD-L1 expression in cytokeratin-positive tumor cells." (PMID 34572882, 2021). "Repeating this process 100 times we attain average pairwise classification accuracies: CD8+ vs. FoxP3+ 74.7%, CD8+ vs. CD68+ 65.3%, and FoxP3+ vs. CD68+ 86.3% (see tumor TC in SI Appendix)." (PMID 34625491, 2021). "CD68+ cells were found to be clustered with tumor cells and dispersed from stromal cells, while CD163+ and CD206+ cells were found to be clustered with stromal cells and dispersed from tumor cells." (PMID 33882057, 2021). "Tumor PD-L1 expression correlated with stromal PD-L1 (p = 0.0003) expression and CD68+ (p = 0.01) macrophage content." (PMID 32974852, 2021). "Our previous work already suggested that CD68+ TAMs can support tumor angiogenesis, primarily before NAC, while stabilin-1+ TAMs rather contribute to the maintenance of lymphatic vessel density after NAC." (PMID 34209679, 2021). "Detailed views of the localisation of IHC positive stained cells are visualised by a checkerboard view for the anti-CD68 IHC and an alpha blending overlay of the segmented T-Ag positive tumour cells." (PMID 34035350, 2021). "Their investigation in colorectal cancer patients revealed an increase in lipid droplets in CD68+CD206+ (M2 markers) tumor-infiltrating myeloid cells when compared with the adjacent non-tumor tissue." (PMID 34063116, 2021). "Treatment with BAY 1895344 was accompanied by a strong apoptotic response as well as a robust immune response, with tumours heavily infiltrated with CD68-positive macrophages." (PMID 34819497, 2021). "Further, BTK was found to be co-expressed to differing degrees with SOX2, CD163, or CD68, indicative of both tumour and immune cell expression of the kinase." (PMID 34645618, 2021). "Immunohistochemistry with anti-macrophage antibodies (anti-Cd68 and MOMA-2) revealed increased numbers of macrophages in tumors of HG mice, and infiltration of tumor-associated macrophages (TAMs) was prevented by administering a miR-467 antagonist." (PMID 33809756, 2021). "As expected, CD73 was mostly expressed on CK8+ tumor cells, but barely expressed on macrophages (CD68+)." (PMID 34838121, 2021).
tumor (continued). "We evaluated the proportions of CD68+ TAMs in the PDAC tumor and adjacent normal pancreatic tissues (n=3) to determine TAM infiltration levels in human PDAC tissues and their correlation with survival outcomes." (PMID 33428605, 2021). "Immunohistochemical analysis of PDM model 2 using CSF1R, CD68, CD204, and CD163 revealed the presence of tumor-associated macrophage markers." (PMID 34063518, 2021). "We also found a higher density of CD68+ macrophage infiltration in perivascular areas compared to the tumor core." (PMID 34654395, 2021). "CD68- and CD163-positive tumor-associated macrophages are reported as key factors in tumor growth and metastasis through releasing chemokines such as inflammatory growth factors." (PMID 34153003, 2021). "Tumor-infiltrating macrophages (TIMs) (CD163+ (M2) and CD68+ (M1)) play a key role in the tumor microenvironment." (PMID 34207243, 2021). "The presence of very numerous CD68± histiocytes in the tumour stroma directly relates to high infiltration by TREM-1± and by CD35± histiocytes (p = .026 and .005, respectively)." (PMID 33769181, 2021). "CRCs contained various numbers of tumor-associated immune cells (TAIs) with SIRPA, CD68, or CD163 expression." (PMID 33799989, 2021). "PD-1H protein was diffusely distributed within the plasma membrane of tumor infiltrating immune cells, and PD-1H expression levels were significantly higher in CD68-positive macrophages than T cells." (PMID 34950702, 2021). "In patient #1, after exposure to anti-PD-1, nodal tissue tumor spatial analysis found CD8+ lymphocytes were almost exclusively on the periphery of the tumor zone, and macrophages at the periphery of the tumor area were a mixture of CD68+ and CD163+." (PMID 34771650, 2021). "Vehicle-treated tumours showed a tissue architecture in which CD68+ macrophages accumulated along the edge of the tumour, while F4/80+ and CD206+ macrophages seemed more intermixed with tumour cells." (PMID 34625563, 2021). "IHC analysis of 176 tumor tissues from OV patients revealed a positive association between TIM expression and the number of CD68+ macrophages in OV tissues." (PMID 34490127, 2021). "Here, we show that strong MHCII expression in tumor cells is coincident specifically with CD68- and CD163-high subsets of NE-low tumors." (PMID 34200100, 2021). "Analysis of immune cells on treated tumours with anti-CD68 antibodies identified a remarkable infiltration of treated tumours in response to BAY 1895344 treatment, in comparison with vehicle treated controls." (PMID 34819497, 2021). "First, we performed multiplex immunofluorescent staining for CD66b+ TANs and CD68+ TAMs in whole tumor sections from 130 patients with ICC." (PMID 33692217, 2021). "When ARID1A mutation status was considered, we identified that mutant cases showed the simultaneous ‘tumour-exclusion’ of both CD68 + TAMs and CD8 + cytotoxic T cells." (PMID 34359755, 2021). "For the first time, we clearly show that CD68−/CD163+ macrophage dominate in OM tumor regions, over other macrophage phenotypes." (PMID 33498676, 2021). "Several studies have used CD163 as an M2 tumor-associated macrophage (TAM) marker and CD68 as a pan macrophage marker(M1+M2)." (PMID 34221962, 2021). "Analysis of normal and tumor tissue from 6 np, 9 pregnant, 11 lactating, 8 involuting, and 10 regressed women aged ≤45 years.IHC, IF, imaging of CD68, CSF-1R, and F4/80." (PMID 33649008, 2021). "(C) IL‐33, CD206 and CD68 were measured by RT‐PCR in non‐tumour and tumour tissues; the correlation of CD206 and IL‐33 in ESCC tissues; N = 20, R2 = .54, P < .01." (PMID 33305406, 2021). "PD-1H protein was predominantly expressed in CD68+ tumor-associated macrophages and expressed at low levels in CD4+ T cells and CD8+ T cells in ESCC tumor tissues." (PMID 34950702, 2021). "By contrast, the number of tumor-infiltrating CD68+M, CD163+M2, and CD47 cells was higher, and these cells were significantly associated with decreased OS." (PMID 34439378, 2021).